CXCL8 (C-X-C motif chemokine ligand 8)
Diseases named in the same sentence as CXCL8 in open-access papers (continued):
Sharing a sentence is not in itself a finding about the gene and the disease.
Sepsis (continued). "High levels of CXCL8 correlated with increased multiorgan failure, sepsis, and mortality." (PMID 36232655, 2022). "CXCL8 and ET-1 may affect sepsis patients complicated with heart failure through a synergistic effect." (PMID 36065195, 2022). "The multivariate logistic regression analysis was carried out with whether the sepsis patient is complicated with heart failure as a dependent variable and with CXCL8, ET-1, LVEF, SV, CO, CI, SOFA score, and APACHE II score as independent variables." (PMID 36065195, 2022). "The antibody treatment exerted anti-inflammatory effects via simultaneous inhibition of IL-6, CXCL8/IL-8, CCL3/MIP-1, TNF-α, and IFN-γ production, and had direct and considerable suppressive effects on excessive CCL and CXCL gene expression associated with sepsis immunopathogenesis." (PMID 38177528, 2024). "However, IL-8 (CXCL8) levels were significantly higher in children with sepsis compared to febrile controls (p<0.05), whereas comparable levels of IL-8 were found in children with sepsis and malaria (p>0.05)." (PMID 35811678, 2022). "However, there are few reports about whether CXCL8 and ET-1 are related to sepsis complicated with heart failure." (PMID 36065195, 2022). "Given that chemokine plasma levels, including of CXCL8 and CCL2 have been shown to be predictive of survival and correlate with sepsis severity, it is tempting to speculate that the loss of DARC expression may affect the outcome in sepsis." (PMID 22912641, 2012). "C-C chemokine ligand 2 (CCL2), C-X-C chemokine ligand 8 (CXCL8)/IL-8, and CXCL2 have been widely studied in sepsis-induced myocardial injury." (PMID 40520010, 2025). "Moreover, another study revealed that septic patients with concurrent heart failure exhibit significantly higher serum levels of CXCL8 and ET-1 compared to those with sepsis alone, suggesting that these biomarkers may play important roles in the pathophysiology of sepsis complicated by HF." (PMID 40526611, 2025). "As sepsis is a systemic intravascular infectious disease, during sepsis, the endothelial cells in the cerebrovascular blood vessels also produce various chemokines, such as CCL2, CCL3, CCL5, CXCL1, CXCL2, CX3CL1, and CXCL8." (PMID 38585633, 2024). "Similar to previous studies, our ICU-sepsis group displayed significantly increased interleukin (IL)-18, IL-1β, IL-6, CXCL-8, IL-10 and MCP-1 compared to either or both of the ICU-non-sepsis patient and healthy cohorts." (PMID 38410714, 2024). "Activated platelets and several potent inflammatory mediators in sepsis and at high concentrations CXCL8 (IL-8) can activate neutrophils to release NETs." (PMID 37954596, 2023). "For example, in sepsis, cytokines such as IL-6, TNF-α, IL-1β, and CXCL8 increase antibody production, vascular permeability, and neutrophil recruitment." (PMID 37600769, 2023). "In the brains of individuals who died from sepsis, expression of CXCL1 was significant in two out of three reported cases, although increased expression of CXCL8/IL-8 was observed in all three cases." (PMID 36613652, 2022). "The objective is to investigate the relationship between sepsis complicated with heart failure and the expression levels of CXC chemokine ligand 8 (CXCL8) and endothelin-1 (ET-1)." (PMID 36065195, 2022). "The close connection of CXCL8 and CXCR2 to sepsis onset and progression makes them biomarkers and therapeutic targets worth exploring." (PMID 36451225, 2022). "There was a clustering of CXCL8, TNFα, CCL4, CCL3, IL-1β and IL-6in the sepsis group indicating a chronic inflammatory response which seems to be mediated mostly by monocytes, whereas the febrile controls had no specific pattern." (PMID 35811678, 2022).
Sepsis (continued). "The results showed that the levels of the pro-inflammatory cytokines IL-6 and IL-8 and several chemokines (CXCL-8, keratinocyte-derived chemokine, and CCL2), and high-mobility group box-1 (HMGB-1) were higher in dogs with sepsis than in the healthy controls." (PMID 33718468, 2021). "AE prominently downregulated CXCL-1, CXCL-8, IL-6, TNF-α, Glu1, and HMGB1 mRNA expression but activated IL-1RN, IL-10, Sirt-1, and Nrf-2 mRNA expression in the lung during sepsis." (PMID 34493741, 2021). "Tumor Necrosis Factor-α (TNF-α), Interleukin-1β (IL-1β), Interleukin-8 (IL-8, CXCL8), and monocyte chemoattractant protein-1 (MCP-1) are notably elevated during the early phases of infection in the case for sepsis, while IL-6 gradually increases over time." (PMID 31547199, 2019). "Indeed, we detected lower levels of CCL1, CXCL8 and CCL3 in plasma from heatstroke patients than in plasma from sepsis patients." (PMID 40084252, 2025). "What's more, in sepsis or aseptic inflammation, overexpressed TLR4 was related to the increased production of CCL1 and CXCL8 in order to recruit monocytes to the sites of infection 34, which was contrary to the inhibited chemotaxis of TLR4high monocytes in our patients with heatstroke." (PMID 40084252, 2025). "CXCL8 is a highly selective pro-inflammatory chemokine, and local and systemic elevations of CXCL8 have been found in various inflammatory diseases as well as in SIRS and sepsis." (PMID 36120307, 2022). "In the second acute-phase response model, the septicemia-like model, an increase in hepatic CXCL1 and CXCL8 gene expression of a similar magnitude as that in the other model was measurable after intraperitoneal (i.p.)injection of LPS, but upregulation declined earlier." (PMID 35336843, 2022). "However, in humans with sepsis, the most important CXCR2 ligand is CXCL8/IL-8, whose blood levels are significantly elevated." (PMID 36613652, 2022). "We detected a prominent effect of AE administration downregulating BALF levels of CXCL-1 (P < 0.05), CXCL-8 (P < 0.01), IL-6 (P < 0.05), IL-10 (P < 0.01), and TNF-α (P < 0.001) and upregulating BALF levels of IL-10 (P < 0.05) and IL-1RN (P < 0.05) during sepsis." (PMID 34493741, 2021). "Aberrant upregulation and activation of pro-inflammatory cytokines and chemokines, including TNF-α, IL-1β, IL-6, IL-8, CCL5, and CXCL8, has been correlated with the progression of chronic inflammatory diseases, such as tumor, sepsis, rheumatoid arthritis, psoriasis, and cytotoxicity." (PMID 29045468, 2017). "Canonically, during sepsis and septic shock mediated by Gram-negative bacteria, one major chemokine implicated in PMN chemotaxis is interleukin 8 (CXCL8), and its receptor, CD182 (CXCR2), is critical for the recruitment of PMNs." (PMID 27802348, 2016). "In our study, GCs were able to limit CXCL8 mRNA, protein in cell lysates, as well as protein secretion into culture media, supporting our hypothesis that GCs could be protective in AH and sepsis if nonhepatic side effects can be limited." (PMID 39619227, 2023).
melanoma (489 papers, 2002 to 2026). A malignant, usually aggressive tumor composed of atypical, neoplastic melanocytes. "Recurrent genes identified that produce melanoma associated chemokines include CXCL8, which is 12.5-fold and fivefold overexpressed in the microsatellites from cases 1 and 2, respectively." (PMID 40717170, 2025). "CXCL12 and CXCL8 have been linked to immunotherapy unresponsiveness for colon cancer and melanoma patients." (PMID 38742117, 2024). "For example, a study found that high CXCL8 expression in melanoma tissues was associated with a 40% increase in tumor invasion and metastasis compared to tumors with low CXCL8 levels." (PMID 39200315, 2024). "Elevated levels of CXCL8 have been linked to increased melanoma aggressiveness and poor clinical outcomes." (PMID 39200315, 2024). "CXCL8 is a gene that codes for a protein and has been linked to diseases such as adult respiratory distress syndrome and melanoma." (PMID 37305753, 2023). "In fact, overexpression of CXCL8 leads to metastatic tumor growth in normal primary melanoma cells and is associated with the transition from RGP to VGP in melanoma." (PMID 37503344, 2023). "The overexpression of CXCL8 in melanoma is associated with disease progression, as an increased expression of CXCL8 and CXCR1 and CXCR2 has previously been associated with melanoma transition from a radial (early stage) to vertical (later stage) growth phase." (PMID 37170733, 2023). "Supportively, in prostate cancer and melanoma, the increasing level of circulating MDSCs are evidenced to be associated poor clinical outcomes and high plasma CXCL8 concentration." (PMID 35372515, 2022). "It has been also shown that ABCB5 (ATP-binding cassette, sub-family B, member 5) contributes to WNT-dependent expression of CXCL8 (C-X-C motif chemokine ligand 8) encoding interleukin-8 to support a slow-cycling and chemoresistant phenotype of melanoma cells." (PMID 31659567, 2020). "Large-scale cohort studies have suggested that elevated plasma or serum CXCL8 was associated with worse prognosis in melanoma, metastatic urothelial carcinoma, and renal cell carcinoma patients." (PMID 33178604, 2020). "In this study, we modulated CXCL-8 levels to mimic the gain or loss of CXCL-8 function in melanoma cell lines." (PMID 23342280, 2012). "Taken together, these data confirm that CXCL-8 expression plays a critical role in regulating multiple cellular phenotypes associated with melanoma growth and metastasis." (PMID 23342280, 2012). "The aggressiveness of malignant melanoma is associated with differential expression of CXCL-8 and its receptors, CXCR1 and CXCR2." (PMID 19401689, 2009). "CXCL8 has been linked to migration of melanoma cells and the induction of matrix metalloproteinase-2 expression, facilitating extracellular matrix degradation and tumor cell migration." (PMID 17261188, 2007). "In addition, CXCL8 expression in melanoma has been associated with angiogenesis and metastasis in pre‐clinical animal models by promoting vascularisation, MMP‐2 activation and anoikis resistance." (PMID 37170733, 2023). "Indeed, high serum levels of CXCL8 and IL-6 in melanoma have been associated with melanoma progression, higher tumor burden, and shorten PFS and OS in patients treated with biochemotherapy, Ipilimumab and Nivolumab." (PMID 35173725, 2022). "One mechanism underlying this is the ability of CXCL8 to promote melanoma cell survival via activating the phosphoinositide 3-kinase (PI3K)/Akt and mitogen-activated protein kinase (MAPK) signalling pathways, key signalling pathways involved in tumour cell survival and proliferation." (PMID 34830780, 2021). "The CXCL8/CXCR2 axis was also found to associate with metastasis of melanoma." (PMID 34503058, 2021). "In cancer, an elevated level of CXCL8 was proved to be associated with worse survival of melanoma." (PMID 33364190, 2020).
melanoma (continued). "Moreover, circulating levels of CXCL8 have previously been associated with poorer prognosis in melanoma and other malignancies, and an early increase in serum CXCL8 after initiation of anti-PD-1 treatment was associated with poor response and survival." (PMID 29157311, 2017). "For example, dacarbazine, the standard therapy for melanoma, causes a “chemokine storm” of CXCL-8 and other CXC chemokines of the same receptor signaling after massive cell death (unpublished data from our laboratory), which is one of the escape mechanisms for developing therapy resistance." (PMID 23342280, 2012). "The mechanism of CIITA induction in melanoma is unknown, but MHC class II expression parallels the expression of chemokines CXCL-1 and CXCL-8 and the nuclear expression of NFκB p50 subunit, which are associated with tumor invasiveness and poor prognosis in melanoma." (PMID 24409178, 2013). "As the most potent neutrophil chemokine, elevated serum CXCL8/IL‐8 levels strongly predict poor outcomes in NSCLC or advanced melanoma patients receiving ICI therapies." (PMID 41491612, 2026). "In melanoma, CXCL8 is a multifunctional cytokine that promotes neo-vascularization, activates MMP-2, and enhances anoikis resistance." (PMID 40717170, 2025). "In melanoma, this activity in CAFs is promoted by increased expression of IL-1β, IL-6, IL-8, C-X-C motif chemokine ligand 8 (CXCL8), and various types of metalloproteinases." (PMID 40725022, 2025). "Cytokine array from SSM2c cells transduced with LV-c or LV-shGLI1 showed a significantly higher secretion of CCL7, CCL2, CCL20 and CXCL8 (IL-8) in CM collected from GLI1-silenced melanoma cells." (PMID 39090759, 2024). "In the following gene expression experiment, E-calponin expression was drastically lower in melanoma tissue as compared to the surrounding normal tissue, while CXCL8, JAK2, STAT3, vimentin, and N-calcineurin expression was significantly increased." (PMID 37215082, 2023). "Marked downregulation of expression of TREM1 and known TREM1 target genes (NFKB1, CCL20, IL6, and CXCL8) was determined in melanoma PDX models treated with VJDT." (PMID 37651197, 2023). "The corresponding ligand to CXCR1 and CXCR2, namely CXCL8, is overexpressed on various cancer cells, including melanoma." (PMID 37170733, 2023). "Melanoma cells constitutively released CXCL8/IL-8, CXCL1/Groα and CXCL2/Gro-β, and CM induced PMN chemotaxis was dependent on CXCR1/2 activation." (PMID 37525065, 2023). "CXCR1 (C-X-C chemokine receptor 1) interacting with CXCL8 (Interleukin-8, IL-8) ligand has a well-known role in the initiation and development of various cancers, including melanoma." (PMID 37240247, 2023). "In melanoma, new markers are continuously exposed through bioinformatics technologies, and multiple markers including IL27, CXCL8, THBS1, and KIT have been identified to be associated with melanoma metastasis and treatment outcomes." (PMID 36438905, 2022). "CXCL8 expression is elevated in many cancers, including melanoma, colon, lung, prostate, and ovarian carcinoma." (PMID 33603130, 2022). "CXCL8 has been described as an important regulator of growth, angiogenesis, migration, and metastasis in melanomas through its binding to CXCR1 and CXCR2 receptors." (PMID 35008395, 2022). "Consistently, Scheibenbogen and co-authors (1995) demonstrated that higher levels of CXCL8 secreted by melanoma cells correlate with poor prognosis." (PMID 35008395, 2022). "Studies have confirmed that CXCL8 enhances vessel density and facilitates distant metastasis in melanoma." (PMID 36612163, 2022). "In vivo studies, it was found that CXCL8 administration increased metastasis in a melanoma mouse model." (PMID 36612163, 2022).
melanoma (continued). "Findings that are in line with ours have been reported for cisplatin-treated melanoma models, and with a therapeutic perspective IL1α and CXCL8 were identified as crucial and pharmacologically targetable drivers." (PMID 34911941, 2021). "These areas show increased expression of CXCL8 as demonstrated by in vivo studies in human melanoma, human pancreatic cancer and ovarian carcinoma." (PMID 33467722, 2021). "Simultaneous blocking of IL-6 and CXCL8 can inhibit CAF-induced human melanoma cell invasiveness using neutralizing antibodies in a 3D spheroid invasion assay." (PMID 35011369, 2021). "presented that the cytotoxic natural killer (NK) cells were assembled in lymph nodes, induced by the expression of CXCL8, and played an essential role in the progression of melanoma to peripheral lymph nodes metastasis, infiltration, and invasion." (PMID 34497764, 2021). "The most significant chemokine in angiogenesis in melanoma is CXCL8, which can have paracrine and autocrine effects when it binds to CXCR1 and CXCR2, expressed on melanoma cells and endothelial cells within the TME." (PMID 34830780, 2021). "As well as the ligands of CCR2 being important in melanomagenesis, UV radiation has been shown to increase the secretion of CXCL8 (formerly known as IL-8), perhaps one of the most important chemokines for melanoma growth and survival." (PMID 34830780, 2021). "CXCL2 and CXCL8 have been correlated to cancer cells chemoresistance, migration, angiogenesis and progression in melanoma, colon and ovary cancers." (PMID 34038868, 2021). "A direct tumor-promoting role has been ascribed to CXCL8 by promoting in vivo melanoma and in vitro pancreatic tumor growth via CXCR2." (PMID 34503058, 2021). "For instance, the level of CXCL8/IL-8 is increased in the melanoma tumor microenvironment, and engineered MAGR-A3 TCR-T cells expressing CXCR2 have shown higher infiltration in xenograft murine models." (PMID 33654227, 2021). "What stood out from our results was how aggressiveness of melanoma cells overexpressing Bcl-xL was mediated by an autocrine effect of CXCL8 on its receptor." (PMID 33803452, 2021). "An increase in CXCL8 expression in melanoma cells, ovarian carcinoma, pancreatic cancer and rhabdomyosarcoma in chronic hypoxia is dependent on the activation of activating protein-1 (AP-1) and NF-κB—in particular, NF-κB p65, NF-κB p50 and c-Jun." (PMID 33467722, 2021). "CXCL8 plays a key role in promoting melanoma motility, and when CXCL8 is blocked, melanoma invasiveness is greatly reduced." (PMID 34830780, 2021). "In melanoma, CXCL8 expression can be regulated by nuclear factor of activated T-cells 1 (NFAT1), signal transducer and activator of transcription 3 (STAT3) and WNT signaling pathway." (PMID 32466509, 2020). "We analyzed the relationship between CXCL8 expression and the prognosis in two phase 3 clinical studies [CheckMate 067 (melanoma); CheckMate 025 (renal cell carcinoma)]." (PMID 33178604, 2020). "By inhibiting the expression or activities of the chemokines, the different investigations indicated that CXCL1 (MGSA) and CXCL8 up-regulated the proliferation of different melanoma cells." (PMID 32582148, 2020). "Lentiviral T cell transduction to express CXCR2 enhanced in vivo homing toward human melanoma in xenograft models, by exploiting the high IL-8/CXCL8 secretion levels." (PMID 33013822, 2020). "For instance, elevated levels of CXCL8/IL-8 in the melanoma microenvironment can be harnessed by engineering T cells to overexpress the matching chemokine receptor CXCR2." (PMID 32570906, 2020). "There is a recent paper focusing on human melanoma xenotransplantation and the role of interleukin 8 (CXCL8) together with bcl-xL on cancer cell dissemination and angiogenesis in the zebrafish." (PMID 31731811, 2019). "The results demonstrate significantly increased production of CXCL1, CXCL2, and CXCL8 protein by A-375 melanoma cells compared to primary melanocytes." (PMID 30870978, 2019).